INS (insulin)
Diseases named in the same sentence as INS in open-access papers (continued):
Sharing a sentence is not in itself a finding about the gene and the disease.
Abdominal obesity (continued). "Thus the aims of our study were to evaluate the changes in glycemia, insulinemia and oxidative stress markers during an OFLT in nondiabetic subjects with abdominal obesity and to analyze the association between postprandial oxidative stress markers and postprandial glucose and insulin responses." (PMID 27537847, 2016). "Haitian American participants were older (P = .032), had higher fasting plasma glucose (P = .036), and A1C (P = .016), but had lower levels of Hs-CRP (P < .001), insulin and HOMA2-IR and lower abdominal obesity (P = .030), than African Americans." (PMID 31667161, 2014). "On the other hand, BMI, fasting insulin, fasting C-peptide and HOMA-IR of the abdominal obesity (+) group were higher than those of the abdominal obesity (−) group." (PMID 23773268, 2013). "The lean group was characterized by a low BMI (mean, 16.7 kg/m2), the absence of central obesity and adiposity, and the lowest C-peptide (median, 463.5 pmol/L) and the lowest insulin resistance." (PMID 40995598, 2025). "In line with other studies, our study sample demonstrated that obese individuals, with a median BMI of 33.8 kg/m2 and waist size of 109 cm depicting abdominal obesity, were more likely to have increased CAP scores, which is reflective of MAFLD and increased insulin resistance." (PMID 39857685, 2025). "The use of BMI and simple body composition measures led to the identification of a distinct lean phenotype that is characterized by a low BMI, poor insulin secretion, and the absence of central obesity and adiposity." (PMID 40995598, 2025). "However, the present study revealed that PCOS women with increased VAT, SAT, VAT/SAT, and WHR had significantly higher levels of fasting insulin in the serum and HOMA-IR compared to women with the normal values of abdominal obesity indices." (PMID 37630842, 2023). "We observed significantly higher levels of fasting insulin in the serum of women with increased VAT, SAT, VAT/SAT, and WHR (p < 0.001, p = 0.007, p < 0.001, and p = 0.005, respectively) compared to women with normal values of abdominal obesity indices." (PMID 37630842, 2023). "Although the underlying mechanisms linking WCR to frailty are not fully understood, they likely involve the negative effects of central obesity on metabolic, hormonal, insulin resistance, and inflammatory pathways." (PMID 37582717, 2023). "IR is usually characterized as increased FBG, fasting insulin, and fasting TG, decreased HDL-C, central obesity (especially increased visceral fat), and so forth, but the roles and importance they played in the quantification of IR have not been fully investigated." (PMID 34537077, 2021). "About 47% of our males and 50% of females with elevated BP were cardiometabolic abnormalities-free, i.e., insulin sensitive, not presenting central obesity, atherogenic dyslipidemia, CRP > 3 mg/L, or hyperuricemia." (PMID 32455627, 2020). "Nevertheless, after adjusting for differences in abdominal obesity, there was no longer a relationship between fiber consumption and insulin resistance." (PMID 29461482, 2018). "Absent from the literature are data from randomized controlled trials that permit determination of whether changes in abdominal obesity and CRF independently mediate the exercise-induced improvement in insulin sensitivity in older adults." (PMID 27936206, 2016). "In the insulin sensitivity model, non-Hispanic whites showed a higher eGFR [β = 4.1 (1.4), p = 0.006], whereas blacks had significantly lower eGFR with abdominal obesity [β = -7.2 (3.3), p = 0.03]." (PMID 27224643, 2016). "In lean groups, subjects with NAFLD were older, more central obesity, and had higher total cholesterol, triglycerides, LDL-c, fasting plasma glucose, 2 h plasma glucose, fasting serum insulin, HOMAIR, CRP, and liver enzymes and had lower adiponectin, HDL-c and eGFR (all P < 0.01)." (PMID 27885258, 2016).
Abdominal obesity (continued). "In sensitivity analyses with normotensive blood pressures defined as ≤120/80mmHg, Mexican American young adults again showed significantly higher albuminuria with abdominal obesity, irrespective of insulin sensitivity, but not for sex-specified albuminuria." (PMID 27224643, 2016). "All mice were fed an isocaloric diet but compared to dMG- mice; dMG+ mice had greater body weight, white fat content, abdominal obesity, and were insulin resistant but not hyperglycemic." (PMID 25668621, 2015). "It was also observed that adolescents with central obesity presented significantly higher levels of TG at 4 hours, insulin and HOMA-IR, than adolescents without this comorbidity." (PMID 23406056, 2013). "No animals in this model presented with altered central obesity, circulating androgen or insulin concentrations." (PMID 21935484, 2011). "In adults, maternal TP exposure resulted in increased insulin secretion to glucose load (P<0.05) and the histological presence of fatty liver (P<0.05) independent of central obesity." (PMID 21935484, 2011). "Waist-hip ratio was also determined; however, it is important to know that neither insulin concentration nor centrally obesity is considered like criteria in children groups in contrast with adolescents groups where some definitions include WHR as criteria." (PMID 18700035, 2008). "However, it revealed a specific lean phenotype that encompassed a low BMI, the absence of central obesity and adiposity, poor insulin secretion, and low insulin resistance." (PMID 40995598, 2025). "Physical activity improves insulin metabolism due to the up-regulation of insulin receptors in muscles leading to the beneficial delivery of glucose and insulin to muscles, reducing central obesity via negative energy balance, and increasing antioxidant capacity." (PMID 37237334, 2023). "It is of note that the pathophysiology of T1DM, which is not characterized by IR at its early stages, is further complicated when IR is added, mainly, but not exclusively, as a consequence of central obesity observed in later stages of patients with T1DM on insulin treatment." (PMID 37511760, 2023). "Therefore, the drop in GCs likely decreased insulin levels, which may be another important mechanism that mediates FGF21 LKO to abrogate OVX-induced central obesity in females." (PMID 37834368, 2023). "Similarly, reduced waist circumference, but not improved cardiorespiratory fitness, predicted insulin sensitivity in participants (n = 59) with abdominal obesity assigned to exercise training." (PMID 34075130, 2021). "Abdominal obesity was measured by increased waist circumference; dyslipidaemia was measured by increased plasma triglycerides and reduced HDL-cholesterol concentrations, and insulin resistance was measured by high fasting plasma glucose and insulin concentrations." (PMID 31906096, 2019). "First, our subjects are all adults with central obesity and older ages, and we may not have recruited appropriate population if the FETUB SNP variants affect insulin resistance earlier before they have been becoming old and obese." (PMID 29390354, 2017). "They found central obesity in 9.2% of children with normal weight and adolescents with WHtR ≥0.5; a multivariate analysis showed they were 1.66, 2.01, 1.47, and 2.5 times more likely to have abnormal plasma LDL-cholesterol, HDL-cholesterol, triglyceride, and insulin levels." (PMID 25395904, 2014). "Androgen deprivation therapy (ADT) leads to a number of adverse effects including deterioration of the musculoskeletal system and increased risk factors for cardiovascular and metabolic complications (e.g. negative lipoprotein profile, reduced insulin sensitivity, abdominal obesity)." (PMID 19951446, 2009).
Abdominal obesity (continued). "In the LIPGENE-SU.VI.MAX study, the ApoB rs512535 and ApoA1 rs670 major G allele homozygotes had increased MetS risk (OR 1.65 and OR 1.42, respectively), which may be explained by their increased abdominal obesity and impaired insulin sensitivity but not dyslipidemia." (PMID 23306188, 2013). "However, insulin sensitivity score increased significantly, waist circumference showed significant decline, in the high MUFA group compared to high carbohydrate group, indicating improved insulin sensitivity and decreased central obesity, respectively, with MUFA-rich diet." (PMID 20671994, 2010). "Waistline, body mass index, insulin and HOMA-IR were significantly higher (all P < 0.05) in type 2 diabetic subjects with abdominal obesity than those without abdominal obesity and controls." (PMID 28814963, 2017). "Seventy-five subjects had abdominal obesity, and were younger and with higher values of weight, height, BMI, WC, SBP, DBP, UA, TG, insulin, and HOMA-IR than subjects without abdominal obesity." (PMID 28106792, 2017). "In summary, our findings suggest that change in abdominal obesity, not CRF, mediate the exercise-induced improvement in insulin sensitivity in older adults." (PMID 27936206, 2016). "In a more recent 12-week parallel-arm study specifically investigating sex-dependent effects of a DHA-enriched fish oil compared with corn oil, fasting insulin levels and HOMA-IR were significantly reduced in adults with abdominal obesity, but no significant sex differences were evident." (PMID 37404855, 2023). "Type 2 diabetic patients with abdominal obesity had higher postprandial AUCs for insulin (LSMD = 86.987, 95% CI = 37.421–136.553, F = 16.739, P < 0.05) and HOMA-IR (LSMD = 37.456, 95% CI = 16.312–58.600, F = 27.012, P < 0.05) than those without abdominal obesity." (PMID 28814963, 2017).
hypertriglyceridemia (498 papers, 2005 to 2026). A laboratory test result indicating elevated triglyceride concentration in the blood. "The condition is thought to stem from hypertriglyceridemia-induced pancreatitis caused by an insulin-deficient state in DKA." (PMID 39791034, 2024). "In the univariate analysis, higher pre-pregnancy BMI, metformin and insulin therapy, third-trimester fasting glucose level, HbA1c, and hypertriglyceridemia were associated with a higher risk of LGA." (PMID 38892511, 2024). "The rs115505361 is mapped on MGAT2 and associated with body mass index, blood proteins, insulin sensitivity and hypertriglyceridemia." (PMID 37669986, 2023). "Cell cultures and rodent models have demonstrated that lipotoxicity, which is associated with hypertriglyceridemia, increases β-cell apoptosis and decreases β-cell insulin secretion." (PMID 38107514, 2023). "One of the diagnostic options for hypertriglyceridemia-induced pancreatitis is heparin and insulin infusion, which significantly decreases the triglyceride level; however, no clinical guidelines for anticoagulant therapy exist to date." (PMID 37371528, 2023). "The enlargement of subcutaneous fat in the lower body of females is associated with protection from glucose-insulin homeostasis and hypertriglyceridemia." (PMID 37047284, 2023). "Lipoprotein lipase, which hydrolyzes triglycerides, is activated by insulin during metabolism, but insulin shortage causes insulin to be inactivated, resulting in hypertriglyceridemia." (PMID 36235206, 2022). "Insulin can be used as a treatment option for acute pancreatitis induced by hypertriglyceridemia, and in turn, hypertriglyceridemia is a common cause of acute pancreatitis." (PMID 36467046, 2022). "Hypertriglyceridemia causes lipotoxicity by accumulating fatty acids in other tissues, which worsens systemic insulin resistance." (PMID 36242012, 2022). "It has been previously documented that overproduction of hepatic TG-rich VLDL and decreased degradation of apolipoprotein B (apoB), a major component of VLDL, in insulin-deficient and/or resistant individuals contribute significantly to hypertriglyceridaemia." (PMID 34365977, 2021). "Under normal circumstances, triglycerides are hydrolyzed by lipoprotein lipase while insufficiency of insulin causes hypertriglyceridemia and hypercholesterolemia." (PMID 33752586, 2021). "The improved insulin sensitivity in ATF6α-deficient DO mice can be due to partial suppression in the development of hypertriglyceridemia." (PMID 33688365, 2021). "In hypertriglyceridemia, increased plasma free fatty acid levels lead to IR and pancreatic β-cell secretion deficiency, resulting in decreased insulin levels." (PMID 34457002, 2021). "SOCS3 is implicated in hypertriglyceridemia and functioning as a repressor of insulin signal transduction by inhibiting phosphorylation of IR as well as inducing degradation of IRS." (PMID 32158492, 2020). "In those respiratory diseases, several bidirectional mechanisms have been proposed to enhance the risk of hypertriglyceridemia, adipose tissue accumulation and insulin resistance, including hypoxia and hypercapnia." (PMID 32275684, 2020). "The downregulation of molecules involved in very low density lipoprotein assembly, which was associated with improved hepatic insulin signaling, also appeared to contribute to the AI-induced attenuation of hypertriglyceridemia." (PMID 28805698, 2017). "Heparin and insulin appear to be a safe, effective, and inexpensive first-line therapy for hypertriglyceridemia-associated acute pancreatitis." (PMID 28225998, 2017). "In summary, alcohol consumption was negatively associated with β-cell function, and high alcohol consumption was associated with an increased risk of hypertriglyceridemia in subjects with only decreased insulin sensitivity or only decreased β-cell function." (PMID 27854254, 2016).
hypertriglyceridemia (continued). "A genetic variant form of the human apoC-III promoter, containing five single base pair changes that makes it less responsive to insulin, has been shown to be associated with severe hypertriglyceridemia." (PMID 26633899, 2015). "Continuous insulin infusion can correct hypertriglyceridemia in T2D patients and markedly reduce the risk of metabolic complications." (PMID 25009601, 2014). "In contrast with our finding, it has been shown that hypertriglyceridemia is associated with impaired free FA suppression, high FA levels, insulin resistance and inhibition of carbohydrate oxidation." (PMID 24566437, 2014). "This severe postprandial hypertriglyceridemia reduces insulin sensitivity and causes more serious metabolic abnormalities." (PMID 23369030, 2013). "In this study the association between hypertriglyceridemia and macrosomia at 32 weeks of gestation was observed that correlated with increase of insulin levels." (PMID 24639763, 2013). "High fructose feeding causes diet-induced alterations of lipid metabolism and decreased insulin sensitivity, hallmark of which is a rapid and profound hypertriglyceridemia." (PMID 16091142, 2005). "APOC3 and ANGPTL3 inhibitors provide potent triglyceride reduction in monogenic and refractory forms, while metabolic agents such as GLP-1 receptor agonists target the hepatic and insulin-resistant components characteristic of polygenic or MASLD-associated hypertriglyceridemia." (PMID 41300829, 2025). "In addition, severe hypertriglyceridemia was specifically associated with DM treated with insulin, which suggested that advanced or uncontrolled DM was the primary metabolic cause of hypertriglyceridemia-induced pancreatitis." (PMID 39634181, 2024). "Insufficient insulin levels can cause hypercholesterolemia and hypertriglyceridemia." (PMID 37892513, 2023). "Deficiency of insulin is often associated with hypertriglyceridemia and hypercholesterolemia." (PMID 36115959, 2022). "These comprehensive findings predominate in determining the severity of defects in individuals and thus significantly influence the prognosis: lipodystrophic disorders are frequently associated with metabolic disturbance, such as insulin resistance and life‐threatening hypertriglyceridemia." (PMID 31774634, 2020). "The hepatic overexpression of Angptl8 causes hypertriglyceridemia and increased insulin secretion." (PMID 31380419, 2019). "Notably, an increased risk of hypertriglyceridemia was observed in participants with only decreased insulin sensitivity or in only decreased β-cell function who consumed high levels of alcohol." (PMID 27854254, 2016). "However, the fact that the additional statistical adjustment for hexose did not materially change the associations between amino acids and hypertriglyceridemia, make it less likely that these associations are mediated through an insulin-resistant state." (PMID 24682914, 2014). "Additionally, insulin is usually prescribed when (i) the other glucose‐lowering medications are ineffective, and/or (ii) hyperglycemia is severe, especially if catabolic states like weight loss, hypertriglyceridemia, and ketosis are present." (PMID 40356047, 2025). "MSG could cause dysregulation of insulin levels, with hypertriglyceridemia as a consequence." (PMID 37892513, 2023). "Previous studies have associated RQ and metabolic outcomes such as hypertriglyceridemia, and similarly to our results, to insulin function, and hepatosteatosis, where higher RQ may increase hepatic fat accumulation and promote liver pathogenesis due to lower fat oxidation." (PMID 34209600, 2021). "Furthermore, ATF4-deficient mice show reductions in hypertriglyceridemia induced by high fructose diets and increased insulin sensitivity, suggesting that ATF4 may act as a modulator of lipid metabolism in the liver." (PMID 25156122, 2014).